MCOLN1 (mucolipin TRP cation channel 1)
Description:
Nonselective cation channel probably playing a role in the regulation of membrane trafficking events and of metal homeostasis. Acts as a Ca(2+)-permeable cation channel with inwardly rectifying activity. Proposed to play a major role in Ca(2+) release from late endosome and lysosome vesicles to the cytoplasm, which is important for many lysosome-dependent cellular events, including the fusion and trafficking of these organelles, exocytosis and autophagy. Required for efficient uptake of large particles in macrophages in which Ca(2+) release from the lysosomes triggers lysosomal exocytosis. May also play a role in phagosome-lysosome fusion (By similarity). Involved in lactosylceramide trafficking indicative for a role in the regulation of late endocytic membrane fusion/fission events. By mediating lysosomal Ca(2+) release is involved in regulation of mTORC1 signaling and in mTOR/TFEB-dependent lysosomal adaptation to environmental cues such as nutrient levels. Seems to act as lysosomal active oxygen species (ROS) sensor involved in ROS-induced TFEB activation and autophagy. Also functions as a Fe(2+) permeable channel in late endosomes and lysosomes. Also permeable to Mg(2+), Na(+), K(+) and Cs(+) (By similarity). Proposed to play a role in zinc homeostasis probably implicating its association with TMEM163 In adaptive immunity, TRPML2 and TRPML1 may play redundant roles in the function of the specialized lysosomes of B cells (By similarity). May contribute to cellular lipase activity within the late endosomal pathway or at the cell surface which may be involved in processes of membrane reshaping and vesiculation, especially the growth of tubular structures. However, it is not known, whether it conveys the enzymatic activity directly, or merely facilitates the activity of an associated phospholipase.
Synonyms: ML1; TRPML1; ML4; MSTP080; MLIV; MST080; TRPM-L1; LECD; MG-2; TRP-ML1
Tractability: Small molecule: a structure with a bound ligand is known; a high-quality ligand is known; it belongs to a druggable protein family. Antibody: UniProt places it where antibodies can reach, with high confidence; its Gene Ontology location is reachable by antibodies, with high confidence; UniProt predicts a signal peptide or a membrane-spanning region. PROTAC: ubiquitination databases record sites on it; a small molecule that binds it is known.
Target class: Voltage-gated ion channel; Ion channel; Transient receptor potential channel
Safety:
Unwanted effects reported when the protein is acted on. In parentheses: how it was acted on, where the effect was seen, and who reports it.
opioid overdose (source: ClinPGx)
Gene: Protein-coding gene on chromosome 19 (7,522,611 to 7,534,009, forward strand). Ensembl gene ENSG00000090674.
Subcellular location: Late endosome membrane; Lysosome membrane; Cytoplasmic vesicle membrane; Cell projection, phagocytic cup; Cytoplasmic vesicle, phagosome membrane; Cell membrane
Subcellular location (Human Protein Atlas): Plasma membrane; Cytosol
Pathways (Reactome):
Transport of small molecules: TRP channels; Transferrin endocytosis and recycling
Gene Ontology:
Molecular function: calcium channel activity; identical protein binding; iron ion transmembrane transporter activity; ligand-gated calcium channel activity; protein binding; intracellularly phosphatidylinositol-3,5-bisphosphate-gated monatomic cation channel activity; monoatomic anion channel activity; monoatomic cation channel activity; NAADP-sensitive calcium-release channel activity; potassium channel activity; sodium channel activity
Biological process: calcium ion export; calcium ion transmembrane transport; intracellular zinc ion homeostasis; iron ion transmembrane transport; phagosome maturation; positive regulation of lysosome organization; protein homotetramerization; cellular response to calcium ion; cellular response to pH; monoatomic cation transport; transferrin transport; calcium-mediated signaling; monoatomic anion transmembrane transport; monoatomic cation transmembrane transport; potassium ion transmembrane transport; sodium ion transmembrane transport
Cellular component: cytoplasmic vesicle membrane; intracellular vesicle; late endosome; late endosome membrane; lysosomal membrane; lysosome; membrane; plasma membrane; receptor complex; endosome membrane; phagocytic cup; phagocytic vesicle membrane
Genetic constraint (gnomAD): Loss-of-function variants: 49 observed, 69.46 expected, observed/expected ratio (o/e) 0.71, 90% interval 0.56 to 0.89. The upper end of that interval is the gene's LOEUF score, 0.89, which puts it in group 3 of 6, group 1 being the genes least tolerant of losing a copy. Missense variants: 586 observed, 815.48 expected, observed/expected ratio (o/e) 0.72, 90% interval 0.67 to 0.77. Synonymous variants: 358 observed, 351.09 expected, observed/expected ratio (o/e) 1.02, 90% interval 0.93 to 1.11.
Gene-disease validity (ClinGen):
ClinGen rates the evidence that MCOLN1 causes each of these diseases.
mucolipidosis type IV (autosomal recessive): Definitive. A lysosomal disease characterized by psychomotor delay, progressive visual impairment, and achlorhydria.
Homologues: Orthologues: chimpanzee MCOLN1 (98% identical), macaque MCOLN1 (97% identical), rabbit MCOLN1 (95% identical), dog MCOLN1 (93% identical), guinea pig MCOLN1 (92% identical), rat Mcoln1 (92% identical), mouse Mcoln1 (91% identical), pig MCOLN1 (91% identical), tropical clawed frog mcoln1 (63% identical), zebrafish mcoln1a (62% identical), zebrafish mcoln1b (58% identical), Drosophila melanogaster CG42638 (39% identical), and 2 more. Paralogues in human: MCOLN3 (52% identical), MCOLN2 (45% identical).
Diseases named in the same sentence as MCOLN1 in open-access papers:
MCOLN1 is named in the same sentence as 114 diseases in open-access papers, as found by Europe PMC text mining. Sharing a sentence is not in itself a finding about the gene and the disease. The quoted sentences say what the papers report.
mucolipidosis type IV (125 papers, 2010 to 2026). "Mucolipidosis type IV (MLIV) is a rare autosomal recessive lysosomal storage disorder caused by pathogenic variants in the MCOLN1 gene on chromosome 19." (PMID 42037965, 2026). "Mutations in MCOLN1, which codes for the TRPML1 channel, are associated with mucolipidosis type IV (MLIV), a disease resulting in impaired development, vision, and motor function." (PMID 40002312, 2025). "Mucolipidosis type IV is an inherited disorder characterized by delayed development and vision impairment, caused by mutations in MCOLN1." (PMID 38295116, 2024). "Mucolipidosis IV (MLIV) is a rare pediatric neurological disease caused by loss-of-function mutations in the MCOLN1 gene." (PMID 38934011, 2024). "Loss-of-function mutations in the MCOLN1 gene causes Mucolipin 1 deficiency, which gives rise to type IV mucolipidosis (ML IV)." (PMID 36672721, 2023). "Of note, the TRPML1 channel (MCOLN1 gene) has been linked to Lewy body disease, and MCOLN1 mutations cause the autosomal recessive lysosomal storage disorder mucolipidosis type IV." (PMID 37998376, 2023). "Mcoln1 is mutated in type IV mucolipidosis, a lysosomal storage disorder, and is believed to regulate late endocytic trafficking and lysosomal acidification among other functions." (PMID 34921635, 2021). "One patient did not have mutations in genes related to ACC, but carried a de novo pathogenic mutation in Mucolipin‐1 (MCOLN1) and was diagnosed with mucolipidosis type IV." (PMID 31578829, 2020). "MCOLN-1 located on human chromosome 19 was identified as the gene mutated in human Mucolipidosis type IV (MLIV), a progressive neurodegenerative disease of children." (PMID 31013784, 2019). "TRPML channels are probably restricted to intracellular vesicles and mutations in the gene (MCOLN1) encoding TRPML1 (mucolipin‐1) cause the neurodegenerative disorder mucolipidosis type IV (MLIV) in man." (PMID 31710715, 2019). "This occurs in the neurodegenerative condition Mucolipidosis IV when loss of function of MCOLN1 inhibits transport of Fe2+ into the cytosol from endosomes and lysosomes." (PMID 30150923, 2018). "Mucolipidosis type IV (MLIV) is a lysosomal storage disease caused by mutations in the MCOLN1 gene, which encodes the lysosomal transient receptor potential ion channel mucolipin-1 (TRPML1)." (PMID 26398942, 2015). "TRPML channels are probably restricted to intracellularvesicles and mutations in the gene (MCOLN1) encoding TRPML1(mucolipin‐1) are one cause of the neurodegenerative disorder mucolipidosis type IV(MLIV) in man." (PMID 26650441, 2015). "Mutations within the human MCOLN1 gene can lead to type IV mucolipidosis (MLIV), a lysosomal storage disease characterized by psychomotor retardation, corneal clouding, retinal degeneration and often iron-deficiency or clinical anaemia." (PMID 23750752, 2013). "Mucolipidosis type IV is a lysosomal storage disorder resulting from mutations in the MCOLN1 gene, which encodes the endosomal/lysosomal Transient Receptor Potential channel protein mucolipin-1/TRPML1." (PMID 23418601, 2013). "Mucolipidosis type IV is caused by autosomal recessive mutations in the MCOLN1 gene." (PMID 37998376, 2023). "Mutations in MCOLN1 gene cause a lysosomal storage disorder called mucolipidosis type IV (MLIV)." (PMID 32425938, 2020). "Mucolipidosis, Type IV (MLIV) is caused by mutations in MCOLN1 (Mucolipin 1), an endo-lysosomal pH sensitive channel that facilitates diffusion of monovalent and divalent ions and facilitates lysosomal and autophagic regulation via its interaction with TFEB and mTOR signaling." (PMID 32351971, 2020). "In this regard, it may deserve to mention that in humans, mutations in the gene encoding TRPML1 channel (MCOLN1) are the cause of the neurodegenerative disorder mucolipidosis type IV (MLIV)." (PMID 26482920, 2016). "A mutation in the MCOLN1 gene encoding TRPML1 causes mucolipidosis type IV." (PMID 27618067, 2016).
mucolipidosis type IV (continued). "MCOLN1/TRPML1 is mutated in Mucolipidosis type IV (MLIV: OMIM 252650), an autosomal recessive LSD characterized by delayed psychomotor development, corneal opacities and neurodegeneration." (PMID 38766825, 2025). "Loss-of-function mutations in the human TRPML1 gene MCOLN1 cause mucolipidosis type IV (MLIV), a rare recessive lysosomal storage disorder (LSD)." (PMID 36825945, 2023). "MCOLN1 was found to have documented links to the nervous system and neurodevelopmental disorders, principally through the role of mutations to this gene in humans to a lysosomal storage disease, mucolipidosis type IV, a severe childhood neurodegenerative disease." (PMID 38094940, 2023). "Mucolipidosis Type IV (MLIV) is caused by a deficiency of the mucolipin cation channel encoded by Mucolipin TRP Cation Channel 1 gene (MCOLN1)." (PMID 35205297, 2022). "These phenotypes also characterize Mucolipidosis type IV (MLIV)—a lysosomal storage disease that stems from the loss of MCOLN1, the gene encoding the human ortholog." (PMID 35406743, 2022). "Mucolipidosis type IV (MLIV) is an autosomal recessive lysosomal storage disorder due to MCOLN1 gene mutations." (PMID 32265740, 2020). "Mucolipidosis type IV (MLIV) is an ultra-rare lysosomal storage disorder caused by biallelic mutations in MCOLN1 gene encoding the transient receptor potential channel mucolipin-1." (PMID 32604955, 2020). "Mucolipidosis type IV (MLIV) is an autosomal-recessive lysosomal storage disease caused by mutations in the MCOLN1 gene, located in humans in the 19p13.2 locus." (PMID 32586947, 2020). "Mucolipidosis type IV (MLIV) is an autosomal recessive developmental disorder caused by mutations in the MLIV gene (MCOLN1), which encodes TRPML1 (mucolipin-1), a member of the TRPML subfamily." (PMID 29238714, 2017). "MCOLN1 deficiency (MCOLN1, autosomal recessive inheritance, MIM #605248) causes the lysosomal storage disorder Mucolipidosis type IV, where both lysosomal and mitochondrial dysfunction have been demonstrated." (PMID 38872485, 2025). "Genetic mutations resulting in loss of TRPML1 function by channel inactivation or mislocalization cause a rare genetic disorder called Mucolipidosis Type IV (MLIV), after which the channel initially was named (mucolipin-1, MCOLN1)." (PMID 32545371, 2020). "Mutations in the MCOLN1 gene, which encodes TRPML1, lead to Mucolipidosis type IV which is a lysosomal storage disorder." (PMID 32411146, 2020). "Mucolipidosis type IV (MLIV) is a neurodegenerative condition, caused by mutations in the MCOLN1 gene that result in the loss of TRPML1 function." (PMID 29233882, 2017). "The same study failed to prove association between PD and founder mutations in the lysosomal enzyme genes HEXA (Tay-Sachs disease) and MCOLN1 (mucolipidosis type IV)." (PMID 24386122, 2013). "Mucolipidosis IV (MLIV) is an ultra-rare, recessively inherited lysosomal disorder resulting from inactivating mutations in MCOLN1, the gene encoding the lysosomal cation channel TRPML1." (PMID 37609073, 2023). "In addition to impaired lysosomal acidification, iron is thought to become trapped within the lysosome, resulting in a functional iron deficiency due to an impairment of the TRPML1 channel (MCOLN1 gene), which occurs in mucolipidosis type IV." (PMID 37998376, 2023). "Mucolipidosis type IV (MLIV) constitutes the most direct link between defective lysosomal Ca2+ release and neurodegeneration, caused by dysfunction of the lysosomal cation channel TRPML1 (also called MCOLN1)." (PMID 35929194, 2022). "Mucolipidosis type IV (MLIV), an ultra-rare neurodevelopmental and neurodegenerative disorder, is caused by mutations in the MCOLN1 gene, which encodes the late endosomal/lysosomal transient receptor potential channel TRPML1 (mucolipin 1)." (PMID 33478506, 2021).
mucolipidosis type IV (continued). "Mucolipidosis type IV (MLIV), an ultra-rare lysosomal storage disease (LSD) primarily found in the Ashkenazi Jewish population, is caused by mutations in the MCOLN1 gene, which encodes the late endosomal/lysosomal transient receptor potential channel TRPML1 (mucolipin 1)." (PMID 33478506, 2021). "For Asah1 (Farber lipogranulomatosis) and Mcoln1 (mucolipidosis IV), where isogenic single and double mutants are both available, severe pathologies were associated only with the double mutant, suggesting that at least a portion of ohnologues share similar functions." (PMID 32435656, 2020). "Loss-of-function mutations in MCOLN1, the gene encoding TRPML1, are the genetic cause of mucolipidosis type IV (MLIV), a lysosomal storage disorder that primarily affects the central nervous system (CNS)." (PMID 41260338, 2025). "Furthermore, the expression level of Ccl5 (RANTES) was increased in Hexa-/-Neu3-/- mice, similar to mouse models of the Niemann Pick type C (Npc1-/-), Gaucher (Gba-/-) and mucolipidosis type IV (Mcoln1-/-), and this increase was reduced after KD and PG treatments." (PMID 40019557, 2025). "Further illustrating the critical and diverse roles of the lysosome, in Mucolipidosis Type IV (ML IV), an autosomal recessive LSD, mutations are caused in the MCOLN1 gene (chromosome 19p13.2-p13.3), which encodes the lysosomal TRPML1 channel." (PMID 41614773, 2025). "Mucolipidosis type IV (MLIV), a prototypical retinal degenerative disorder, is an autosomal recessive lysosomal storage disorder (LSD) caused by mutations in the MCOLN1 gene." (PMID 38020430, 2023). "Mucolipidosis type IV (MLIV) is a neurodevelopmental and neurodegenerative disorder caused by the loss of function of mucolipin 1 (TRPML1), a lysosomal channel encoded by the MCOLN1 gene." (PMID 35159355, 2022). "MCOLN1 gene (encodes mucolipin-1, MLN1) mutations cause Mucolipidosis type IV (MLIV) characterized by late endosome/lysosome accumulation." (PMID 32375321, 2020). "Mucolipidosis type IV (MLIV) is a lysosomal disease caused by mutations in the MCOLN1 gene that encodes the endolysosomal transient receptor potential channel mucolipin-1, or TRPML1." (PMID 32586947, 2020). "TRPML1, the founding member of this subfamily, was named after the channelopathy, mucolipidosis type IV (MLIV), caused by mutations in the TRPML1 gene (MCOLN1)." (PMID 30591696, 2018). "CUP-5 is the sole orthologue of mammalian TRPML1 that is encoded by MCOLN1, mutations in which cause Mucolipidosis type IV (MLIV) in humans." (PMID 20540742, 2010). "Recessive loss of function mutations in MCOLN1, encoding for TRPML1, lead to mucolipidosis type IV (MLIV), a lysosomal storage disorder characterized by motor neurodegeneration, vision impairment and mental retardation, due to defective biogenesis of lipid-containing vacuoles." (PMID 40282211, 2025). "Similarly, defects in lysosomal membrane proteins such as NPC1, LAMP2 and MCOLN1 cause Niemann-Pick type C (NPC), Danon and Mucolipidosis type IV (MLIV) diseases, respectively." (PMID 32375321, 2020). "Only one patient was tested once with the disorder in the MCOLN1 gene, or Mucolipidosis type IV, and had no significant changes in either parameter." (PMID 28293191, 2017). "These contact sites are adversely affected by genetic defects in MCOLN1 gene which codes for the lysosomal transient receptor potential (TRP) cation channel, mucolipin subfamily, member 1 (TRPML1), resulting in a severe lysosomal storage disorder mucolipidosis type IV." (PMID 37737664, 2023). "Mucolipidosis type IV (MLIV) is a lysosomal storage disorder caused by loss-of-function mutations in the MCOLN1 gene encoding the endolysosomal non-selective cation channel TRPML1." (PMID 35875350, 2022).
mucolipidosis type IV (continued). "However, TFEB overexpression failed to induce cellular clearance in a mucolipidosis IV model characterized by mutations in the MCOLN1 gene, suggesting that TFEB-mediated lysosomal exocytosis and clearance may occur through the activation of the Ca2+ channel TRPML1." (PMID 32276321, 2020).
lysosomal storage disorder (60 papers, 2010 to 2026). "Loss of MCOLN1 channel function results in a detrimental lysosomal storage disease marked by infantile mental retardation, corneal opacities, strabismus, and delayed motor development." (PMID 32545371, 2020). "Mucolipidosis type IV (MLIV; #252650), is a rare autosomal recessive lysosomal storage disease (LSD) resulting from loss-of function mutations in the MCOLN1 gene (*605248), which encodes for mucolipin-1 (ML1)." (PMID 32604955, 2020). "MLIV is an autosomal recessive, neurodegenerative lysosomal storage disorder, which is due to mutations in the gene MCOLN1." (PMID 26818117, 2015). "MLIV is a lysosomal storage disorder resulting from loss of function mutations in the MCOLN1 gene." (PMID 38020430, 2023). "A recent study that assessed the association of specific founder mutations in each of the lysosomal storage disorder genes HEXA, SMPD1 and MCOLN1, in 938 Ashkenazi Jewish (AJ) PD patients and 282 matched AJ controls, reported SMPD1 L302P as a risk factor for PD in the AJ population." (PMID 25933391, 2015). "In the current study we performed a genetic analysis of four lysosomal storage disorder genes including GBA, HEXA, SMPD1, MCOLN1 in 231 brain autopsies from the New York Brain Bank at Columbia University." (PMID 25933391, 2015).
glioblastoma (18 papers, 2019 to 2025). The most malignant astrocytic tumor (WHO grade IV). "A strong association has been shown between loss of/reduced TRPML-1 mRNA-expression and poor survival, revealing the potential application of MCOLN1 as a prognostic biomarker in glioblastoma patients." (PMID 31867325, 2019).